MRPL49 (mitochondrial ribosomal protein L49)
Synonyms: L49mt; MRP-L49; NOF; C11orf4; NOF1; mL49; COXPD60
Tractability: Small molecule: a structure with a bound ligand is known. PROTAC: its protein half-life has been measured.
Gene: Protein-coding gene on chromosome 11 (65,122,183 to 65,127,371, forward strand). Ensembl gene ENSG00000149792.
Subcellular location: Mitochondrion
Pathways (Reactome):
Metabolism of proteins: Mitochondrial ribosome-associated quality control; Mitochondrial translation elongation; Mitochondrial translation initiation; Mitochondrial translation termination
Gene Ontology:
Molecular function: protein binding; structural constituent of ribosome
Biological process: mitochondrial translation; translation
Cellular component: mitochondrial large ribosomal subunit; mitochondrial ribosome; mitochondrion; mitochondrial inner membrane; ribosome
Genetic constraint (gnomAD): Loss-of-function variants: 13 observed, 19.06 expected, observed/expected ratio (o/e) 0.68, 90% interval 0.44 to 1.09. The upper end of that interval is the gene's LOEUF score, 1.09, which puts it in group 4 of 6, group 1 being the genes least tolerant of losing a copy. Missense variants: 190 observed, 226.16 expected, observed/expected ratio (o/e) 0.84, 90% interval 0.75 to 0.95. Synonymous variants: 104 observed, 91.39 expected, observed/expected ratio (o/e) 1.14, 90% interval 0.97 to 1.34.
Homologues: Orthologues: chimpanzee MRPL49 (99% identical), macaque MRPL49 (97% identical), pig MRPL49 (87% identical), guinea pig MRPL49 (85% identical), rat Mrpl49 (84% identical), mouse Mrpl49 (83% identical), dog MRPL49 (69% identical), tropical clawed frog mrpl49 (60% identical), zebrafish MRPL49 (54% identical), Drosophila melanogaster mRpL49 (37% identical), Caenorhabditis elegans mrpl-49 (30% identical).
Diseases named in the same sentence as MRPL49 in open-access papers:
MRPL49 is named in the same sentence as 23 diseases in open-access papers, as found by Europe PMC text mining. Sharing a sentence is not in itself a finding about the gene and the disease. The quoted sentences say what the papers report.
breast carcinoma (1 paper, 2024). "Interestingly, enrichment of the glycolysis pathway correlated with EMT in primary breast cancer, which could suggest that downregulation of MRPL49 in invasive cells is linked to EMT and metastatic progression." (PMID 39354291, 2024). "In breast cancer, MRPL49 expression appears to support tumour development, but reduces metastatic capacity." (PMID 39354291, 2024). "Specifically, a study observed upregulation of MRPL49 in non-invasive breast cancer cells, and downregulation in invasive cells compared to normal breast epithelial cells." (PMID 39354291, 2024).
developmental delay (1 paper, 2025).
Encephalopathy (1 paper, 2025). Encephalopathy is a term that means brain disease, damage, or malfunction. "Mitochondrial ribosomal proteins such as MRPL49 (mitochondrial ribosomal protein L49) and DAP3 (death associated protein 3) have been associated with encephalopathy and progressive SNHL." (PMID 41191133, 2025).
Hearing impairment (1 paper, 2025). A decreased magnitude of the sensory perception of sound. "Patients with MRPL49 biallelic variants present consistently with an intellectual disability syndrome that includes primary ovarian insufficiency in females and hearing impairment present in 6/9 patients in the initial discovery study." (PMID 41191133, 2025).
Intellectual disability (1 paper, 2025).
learning disability (1 paper, 2025). A group of disorders that affect a person's ability to learn or process specific types of information which is in contrast to his/her apparent level of intellect. "We identify bi-allelic variants in the mitoribosomal large subunit encoded by MRPL49 as a cause of a pleiotropic presentation of hearing loss, ovarian failure, learning disability, and leukodystrophy and support these findings with genetic and functional data." (PMID 40043708, 2025). "In summary, we describe bi-allelic variants in MRPL49 associated with a pleiotropic phenotype, including SNHL, POI, leukodystrophy, learning disability, and retinopathy in unrelated families." (PMID 40043708, 2025). "Our cumulative data have determined that bi-allelic variants in MRPL49 are associated with a complex variable mitochondrial phenotype, characterized by SNHL, POI, leukodystrophy, retinopathy, and learning disability." (PMID 40043708, 2025).
lung carcinoma (1 paper, 2024). "Altered MRPL49 expression has been observed in breast and lung cancer, with a potential link to metastasis." (PMID 39354291, 2024). "However, an alternate pattern of MRPL49 expression was observed in a study utilising TCGA lung cancer data." (PMID 39354291, 2024).
ovarian carcinoma (1 paper, 2021). A malignant neoplasm originating from the surface ovarian epithelium. "Additionally, MRPL38 and MRPL49, among other MRPs, were confirmed to be significantly related to the invasion and prognosis of ovarian cancer." (PMID 33934540, 2021).
Parkinson disease (1 paper, 2022). A progressive degenerative disorder of the central nervous system characterized by loss of dopamine producing neurons in the substantia nigra and the presence of Lewy bodies in the substantia nigra and locus coeruleus. "A study has found that MRPL49 shows altered proteolytic processing by dopamine treatment in Parkinson’s disease." (PMID 36171891, 2022).
tumor (2 papers, 2020 to 2024). "Specifically, MRPL49 expression was increased in late-stage LUAD and LUSC tumours compared to normal lung samples." (PMID 39354291, 2024).
cancer (1 paper, 2024). A tumor composed of atypical neoplastic, often pleomorphic cells that invade other tissues. "Likewise, for the other MRPLs that appear to have different functions between cancer types (e.g. MRPL19, MRPL37 and MRPL49)." (PMID 39354291, 2024).
MRPL49 also shares sentences with these, for which no sentence is quoted: infection (1 paper); intellectual disability syndrome (1); leukodystrophy (1); microcephaly (1); neurodegenerative disease (1); ovarian failure (1); Perrault syndrome (1); Retinal dystrophy (1); retinopathy (1); retinopathy of prematurity (1); sensorineural hearing loss (1); trichothiodystrophy (1).